BMAL1 (basic helix-loop-helix ARNT like 1)
Diseases named in the same sentence as BMAL1 in open-access papers (continued):
Sharing a sentence is not in itself a finding about the gene and the disease.
lung carcinoma (21 papers, 2013 to 2025). "Furthermore, the association between impairment of BMAL1 expression and disruption of circadian rhythms in lung function suggests that circadian disruption may be involved in lung cancer through alterations of BMAL1 expression." (PMID 26253128, 2015). "To illustrate, in A549 lung cancer cells, BMAL1 knockdown stimulates cancer cell invasion, whereas BMAL1 overexpression lowers cellular invasion." (PMID 32231148, 2020). "For example, BMAL1 inhibits entry into S-phase of the cell cycle in human colon cancer and suppresses cell invasion in A549 lung cancer cells by inhibiting the phosphoinositide 3-kinase-Akt-matrix metalloproteinase (MMP)-2 signaling pathway." (PMID 32231148, 2020). "We demonstrated that TGF-β1-induced expression of PAI1, which is overexpressed in pulmonary fibrosis and lung carcinoma, is inhibited upon inactivation of BMAL1 in alveolar epithelial cells as well as lung fibroblasts." (PMID 26753996, 2016). "To accomplish this, we co-expressed Bmal1 and Bcl-w in lung cancer cells, and examined MMP-2 levels and cellular invasiveness." (PMID 23563360, 2013). "Inhibition of lung cancer metastasis and progression is elicited by Per2 and Bmal1." (PMID 39012661, 2024). "In addition, several lines of evidence have shown that BMAL1 decreases the migration and invasion of tumor cells in several types of cancer, including tongue squamous cell carcinoma and lung cancer." (PMID 32231148, 2020). "To determine whether Bmal1 influences cellular invasiveness, we overexpressed Bmal1 in human A549 lung cancer cells." (PMID 23563360, 2013). "Various molecular pathways and genes such as BMAL1, SIRT1, HLF, and PER1 and their implications in aging, circadian rhythms, and lung cancer will also be discussed." (PMID 39812541, 2025). "Circadian rhythms control metabolism; mutations in BMAL1 or the lack of PER2 and BMAL1 increase MYC transcription, glucose consumption, and lactate excretion, which speeds up the development of lung cancer." (PMID 41267990, 2025).
acute myeloid leukemia (20 papers, 2015 to 2024). Acute myeloid leukemia (AML) is a group of neoplasms arising from precursor cells committed to the myeloid cell-line differentiation. "A correctly functioning molecular clockwork has been shown to endow normal and malignant hematopoietic cells and the core transcription factors CLOCK and BMAL1 are essential for growth of acute myeloid leukemia cells." (PMID 37620852, 2023). "CLOCK and BMAL1 were necessary for cell proliferation and stemness maintenance in acute myeloid leukemia." (PMID 37524704, 2023). "CLOCK and BMAL1 showed oncogenic potential in acute myeloid leukemia." (PMID 37524704, 2023). "In addition, previous studies have revealed CLOCK and BMAL1 as key regulators for acute myeloid leukemia (AML) by contributing to proliferation and stemness." (PMID 35246220, 2022). "In an earlier study using a murine model of acute myeloid leukemia (AML), disruption of Clock and/or Bmal1 using RNAi in leukemic stem cells (LSCs) in vivo was shown to produce anti-leukemic effects, including impaired proliferation, enhanced myeloid differentiation, and depletion of LSCs." (PMID 36430659, 2022). "It has been demonstrated that knockdown of either BMAL1 or CLOCK has been observed to induce cell cycle arrest and apoptosis in cancer stem cells in a patient-derived glioblastoma cell or murine leukemia stem cells in acute myeloid leukemia." (PMID 35984550, 2022). "Epigenetic inactivation of Bmal1 can often be found in hematologic malignancies, such as diffuse large B-cell lymphoma, acute lymphocytic leukemia (ALL), non-Hodgkin's lymphoma (NHL) and acute myeloid leukemia (AML)." (PMID 26288701, 2015). "In another recent study, it was shown that the circadian rhythm transcription factors BMAL1 and CLOCK were demonstrated to be essential for the formation of leukemia stem cells in acute myeloid leukemia (AML), and disruption of circadian pathway components might cause anti-leukemic effects." (PMID 38892035, 2024). "In acute myeloid leukemia (AML), PER2, PER3, and CRY levels are reduced due to reduced expression of CCAAT/enhancer-binding proteins (C/EBPs), while BMAL1, CLOCK, and PER1 levels increase." (PMID 34966277, 2021). "A recent finding of targeting BMAL1 and CLOCK for acute myeloid leukemia (AML) therapy indicates further the pro-cancerous option of clock components." (PMID 28108951, 2017). "It inhibits ferroptosis in TSCC cells by inhibiting miR-125b-5p and enhancing SLC7A11, while in acute myeloid leukemia (AML), muscle ARNT-Like protein-1 (Bmal1) prevented RSL3-induced ferroptosis through EZH2-mediated EBF3 methylation to inhibit the expression of EBF3 and ALOX15." (PMID 39518098, 2024).
asthma (20 papers, 2017 to 2026). "They found that postnatal BMAL1 loss alone is sufficient to compromise the immune system’s ability to fight viral infections in the lung and cause asthma." (PMID 41522721, 2026). "In murine asthma models, the deficiency of BMAL1 is correlated with heightened airway inflammation and augmented airway resistance." (PMID 41473388, 2025). "Together, this suggests a significant association between asthma progression and BMAL1 dysfunction in the airway epithelium." (PMID 41208877, 2025). "For instance, BMAL1 deficiency worsened viral bronchiolitis and promoted asthma-like airway changes." (PMID 37108640, 2023). "In this study, we used PM2.5 isolated from the atmosphere and carbon particles as particulate matter, we aimed to understand the role of BMAL1 and autophagy in asthma and PM2.5-challenged murine models and explore the underlying mechanisms." (PMID 36803515, 2023). "Bmal1-deficient macrophages produce more asthma-associated CCL2 and CXCL10 upon LPS stimulation than wild-type macrophages." (PMID 32595651, 2020). "Importantly, we also observed that BMAL1 deficiency was associated with elevated T1 inflammatory cytokines in knockout mice, suggesting a potential role of BMAL1 loss in driving asthma endotype switching." (PMID 41208877, 2025). "Interestingly, we also observed that the ERK pathway, another pathway associated with asthma, was significantly activated after BMAL1 knockdown." (PMID 41208877, 2025). "The increased susceptibility of the knockout was not a result of an aberrant fetal development due to embryonic loss of Bmal1, as inducible post-natal deletion of the Bmal1 gene also led to enhanced SeV replication, and as a result, developed more extensive asthma-like airway changes." (PMID 31756974, 2019). "KEGG pathway analyses revealed that P. acnes-induced and Bmal1-regulated inflammations were associated with activation of NF-κB and NF-κB-related signaling pathways (such as tuberculosis, rheumatoid arthritis, leishmaniasis, inflammatory bowel disease, epstein-barr virus infection, and asthma)." (PMID 35414779, 2022). "It then focuses on unresolved scientific questions regarding the function of the BMAL1 gene in asthma pathogenesis, aiming to contribute to the future development of metabolic rhythm-based strategies as novel targets for asthma diagnosis and treatment." (PMID 42274140, 2026). "Our analysis revealed that individuals diagnosed with severe asthma presented markedly lower BMAL1 levels than individuals with moderate asthma did." (PMID 41208877, 2025). "To test this, we deleted BMAL1 in airway epithelial cells and established a mouse model to examine how its loss alters GC responsiveness in HDM-induced asthma." (PMID 41208877, 2025). "Collectively, these findings demonstrate BMAL1 is essential for the anti-inflammatory effects of GC therapy in asthma by sustaining GR phosphorylation." (PMID 41208877, 2025). "Here we demonstrated that SR1001 prevents CCL11/CCR3-induced ERK phosphorylation in eosinophils, possibly by increasing BMAL1 and thereby impeding this crucial pathomechanism of asthma." (PMID 40131242, 2025). "To further validate the therapeutic potential of DUSP4 inhibition in vivo, we administered the DUSP4 inhibitor BCI to Bmal1-/- mice with HDM-induced asthma in combination with DEX treatment." (PMID 41208877, 2025). "In adult mice, cellular clocks target pathways highly relevant to asthma pathophysiology and Bmal1 deletion increases inflammatory response, worsens lung function, and impacts survival outcomes." (PMID 38942729, 2024). "The asthma-challenged Bmal1−/− mice had higher autophagy marker expression than that in asthma-challenged Bma1lwt/wt mice." (PMID 36803515, 2023).
asthma (continued). "Staining of lung tissues revealed that asthma-challenged Bmal1−/− mice displayed more severe bronchial epithelial cell hypertrophy, collagen deposition, and MUC5AC protein secretion compared with asthma-challenged Bmal1wt/wt mice." (PMID 36803515, 2023). "Using the ovalbumin model of allergic asthma, BMAL1-LysM−/− mice demonstrated markedly increased asthma features (increased lung inflammation, eosinophils as well as increased IL-5 levels in the lung and serum)." (PMID 37314017, 2023). "BMAL1 knockout mice displayed heightened asthma-like airway changes after virus infection, including increased airway resistance and mucus production." (PMID 36803515, 2023). "BMAL1 protein levels were also reduced in lung tissues of asthma or/and carbon particle-challenged mice." (PMID 36803515, 2023). "Our findings suggest that there are increased IL-6 levels in nocturnal asthma resulting from inhibition of the BMAL1/FOXA2 signalling pathway in airway epithelial cells." (PMID 36505412, 2022). "In this study, BMAL1 silencing lead to more pronounced asthma-typical airway changes, which suggests a role for BMAL1 in the regulation of lung-specific antiviral responses and the subsequent development of asthmatic symptoms." (PMID 32012758, 2020). "Animal models of asthma have indicated that the expression of the clock gene BMAL1 plays a role in eosinophil trafficking and the production of the cytokine IL-5, which is a target of multiple asthma drugs and has been shown to be under epigenetic regulation." (PMID 32662059, 2020). "This study highlights the complex interaction between the circadian clock and the pathophysiological features of asthma, particularly highlighting the role of BMAL1 in the regulation of MUC1 expression, which is a key component in the airway’s mucosal defense mechanism." (PMID 41473388, 2025). "Based on these findings, we hypothesized that BMAL1 deletion disrupts GR signaling and promotes GC resistance in asthma." (PMID 41208877, 2025). "Thus, both in vitro and in vivo results suggested that asthma and exposure to particulate matters reduced BMAL1 protein expression." (PMID 36803515, 2023). "Ehlers and colleagues used a different asthma model to investigate the role of BMAL1 in asthma." (PMID 37314017, 2023). "This suggests that the disorder of circadian clock genes and low expression of BMAL1 may lead to an increase in cytokines such as IL-6 and induce nocturnal asthma symptoms." (PMID 36505412, 2022). "Indeed, in other cells from the myeloid lineage, such as eosinophils, a more inflammatory phenotype derived from BMAL1 deletion induced more severe asthma attacks, as given by an exaggerated Th2-driven immune response." (PMID 36293015, 2022). "Since the epithelial response to LPS in the lung determines the development and severity of asthma, Bmal1 regulation of the epithelial response to LPS may potentially explain the circadian nature of this disease." (PMID 32595651, 2020). "The findings suggest that the circadian regulation of MUC1 by BMAL1 may hold significant implications for understanding the temporal dynamics of asthma symptoms and potentially inform therapeutic strategies targeting the circadian clock to mitigate asthma pathologies." (PMID 41473388, 2025). "To assess the role of BMAL1 in allergic airway inflammation, we established an HDM-induced asthma model using wild-type (WT) mice and Bmal1-/- mice." (PMID 41208877, 2025). "Natural medicines, such as psoralen and BBR, have been found to restore circadian rhythm balance by modulating the expression of BMAL1 and REV‐ERBα, thereby alleviating asthma inflammation." (PMID 41473388, 2025).
asthma (continued). "However, the role of BMAL1 in developing PM2.5-induced asthma is unknown." (PMID 36803515, 2023). "Ehlerset al. showed a reduction in expression of BMAL1, PER2 and NR1D1 in bronchial brushings from mild/moderate asthma patients; however, only a single time point was evaluated." (PMID 37404842, 2023). "The OVA-induced asthma model with a circadian rhythm disorder and 16HBE cells treated with serum shock showed an increase in IL-6 levels and a negative correlation with BMAL1 and FOXA2." (PMID 36505412, 2022). "Consequently, our findings suggest that the absence of BMAL1 results in the resistance of airway epithelial cells to GC due to the inhibition of GR phosphorylation via the DUSP4-p38MAPK axis in HDM-induced asthma." (PMID 41208877, 2025).
bipolar disorder (20 papers, 2009 to 2024). A disorder of the brain that causes unusual shifts in mood, energy, activity levels and the ability to carry out day-to-day tasks. "The studied clock gene CLOCK (Circadian Locomotor Output Cycles Kaput) and its binding partner BMAL1 (also known as Aryl hydrocarbon receptor nuclear translocator-like protein 1 or ARNTL1) were associated with bipolar disorder phenomena in genetic studies." (PMID 28588455, 2017). "A report on SNP markers by the Psychiatric Genomics Consortium (Bipolar Disorder and Schizophrenia Working Group) stated that a SNP in Bmal1 could help to differentiate genetic risk for bipolar disorder and schizophrenia." (PMID 36593479, 2023). "Some studies reported other clock genes associated with bipolar disorder (such as Bmal1 and Per3)." (PMID 28468274, 2017). "Recent research has identified deficiencies in key circadian rhythm genes, including CLOCK, PER, CRY, and BMAL1, in bipolar disorder, depression, and autism spectrum disorder." (PMID 39584972, 2024). "The gene expression levels of CHRONO and BMAL1 have been shown to be used to discriminate individuals with bipolar disorders from normal controls." (PMID 39454958, 2024). "This is revealing, as abnormalities in circadian rhythms are considered to play a potential underlying role in bipolar disorder, as many genes associated with bipolar disorder including CLOCK, PER3 and BMAL1 are regulated in a circadian manner." (PMID 37730845, 2023). "While further studies are required, so far, variations of Per3 have been associated with age of onset of mood disorders, response to treatment and circadian mood variations and Per 3, Bmal1, CLOCK, Nr1d1 and Nr1f2 have all been linked to bipolar disorder." (PMID 23521808, 2013). "Associations between seasonal affective disorder (SAD), a variant of bipolar disorder, and polymorphisms in the clock genes PER2, ARNTL/BMAL1, and NPAS2 have been reported." (PMID 19909500, 2009). "Aberrant DNA methylation of Bmal1 was observed in bipolar disorder and AD patients." (PMID 36593479, 2023). "This SNP in Bmal1 was also correlated with morbidity in bipolar disorder and schizophrenia." (PMID 36593479, 2023). "Activation of Bmal1 is also a biological target for lithium in the treatment of bipolar disorder." (PMID 36593479, 2023). "Several studies have shown association of clock gene polymorphisms with mood disorders, including associations of: MDD with Per2, Cry1, and Rora; seasonal affective disorder with Bmal1, Per2, Cry2, and Npas2; and bipolar disorder with Clock, Bmal1, Per3, Rev-erbα, and Rorb." (PMID 37441675, 2023). "Similarly, a reduction in the amplitude of expression rhythms of genes such as Bmal1 was detected in the saliva of patients with bipolar disorder." (PMID 36593479, 2023). "Furthermore, a SNP in Bmal1 and a SNP in Tim have also been identified as having a link with bipolar disorder." (PMID 28468274, 2017). "In additional work where we used an expanded Convergent Functional Genomics approach in a mouse pharmacogenomic model for bipolar disorder, we identified a series of other clock genes (ARNTL/BMAL1, CRY2, CSNK1D, and CCR4/nocturnin) as potential bipolar candidate genes." (PMID 19909500, 2009).